POLH (DNA polymerase eta)
Description:
DNA polymerase specifically involved in the DNA repair by translesion synthesis (TLS). Due to low processivity on both damaged and normal DNA, cooperates with the heterotetrameric (REV3L, REV7, POLD2 and POLD3) POLZ complex for complete bypass of DNA lesions. Inserts one or 2 nucleotide(s) opposite the lesion, the primer is further extended by the tetrameric POLZ complex. In the case of 1,2-intrastrand d(GpG)- cisplatin cross-link, inserts dCTP opposite the 3' guanine. Particularly important for the repair of UV-induced pyrimidine dimers. Although inserts the correct base, may cause base transitions and transversions depending upon the context. May play a role in hypermutation at immunoglobulin genes. Forms a Schiff base with 5'-deoxyribose phosphate at abasic sites, but does not have any lyase activity, preventing the release of the 5'-deoxyribose phosphate (5'-dRP) residue. This covalent trapping of the enzyme by the 5'-dRP residue inhibits its DNA synthetic activity during base excision repair, thereby avoiding high incidence of mutagenesis. Targets POLI to replication foci.
Synonyms: RAD30; RAD30A; XPV; XP-V
Tractability: Small molecule: a structure with a bound ligand is known; a high-quality ligand is known. PROTAC: UniProt records ubiquitination sites on it; ubiquitination databases record sites on it; a small molecule that binds it is known.
Target class: Enzyme; Transferase
Gene: Protein-coding gene on chromosome 6 (43,575,537 to 43,620,523, forward strand). Ensembl gene ENSG00000170734.
Subcellular location: Nucleus
Subcellular location (Human Protein Atlas): Nucleoplasm
Pathways (Reactome):
DNA Repair: HDR through Homologous Recombination (HRR); Termination of translesion DNA synthesis; Translesion Synthesis by POLH
Gene Ontology:
Molecular function: DNA polymerase activity; DNA-directed DNA polymerase activity; protein binding; damaged DNA binding
Biological process: DNA synthesis involved in DNA repair; response to UV-C; translesion synthesis; DNA repair; error-free translesion synthesis; regulation of DNA repair; DNA damage tolerance
Cellular component: nucleoplasm; nucleus; replication fork; site of double-strand break
Genetic constraint (gnomAD): Loss-of-function variants: 41 observed, 62.91 expected, observed/expected ratio (o/e) 0.65, 90% interval 0.51 to 0.85. The upper end of that interval is the gene's LOEUF score, 0.85, which puts it in group 3 of 6, group 1 being the genes least tolerant of losing a copy. Missense variants: 722 observed, 849.55 expected, observed/expected ratio (o/e) 0.85, 90% interval 0.8 to 0.9. Synonymous variants: 272 observed, 305.9 expected, observed/expected ratio (o/e) 0.89, 90% interval 0.81 to 0.98.
Gene-disease validity (ClinGen):
ClinGen rates the evidence that POLH causes each of these diseases.
xeroderma pigmentosum variant type (autosomal recessive): Definitive.
Homologues: Orthologues: chimpanzee POLH (99% identical), macaque POLH (97% identical), dog POLH (87% identical), guinea pig POLH (82% identical), pig POLH (82% identical), mouse Polh (79% identical), rat Polh (77% identical), rabbit POLH (73% identical), tropical clawed frog polh (51% identical), zebrafish polh (50% identical), Drosophila melanogaster PolH (34% identical), Caenorhabditis elegans polh-1 (26% identical). Paralogues in human: POLI (22% identical), POLK (19% identical), REV1 (19% identical), ESCO1 (7% identical), ESCO2 (7% identical).
Diseases named in the same sentence as POLH in open-access papers:
POLH is named in the same sentence as 41 diseases in open-access papers, as found by Europe PMC text mining. Sharing a sentence is not in itself a finding about the gene and the disease. The quoted sentences say what the papers report.
xeroderma pigmentosum (20 papers, 2010 to 2025). Xeroderma pigmentosum (XP) is a rare genodermatosis characterized by extreme sensitivity to ultraviolet (UV)-induced changes in the skin and eyes, and multiple skin cancers. "Autosomal recessive inheritance of POLH mutations is the cause of the xeroderma pigmentosum variant, a cancer predisposition syndrome." (PMID 36672916, 2023). "Inherited defects in the gene encoding POLH (a.k.a., XPV) are associated with the rare, sun-sensitive, cancer-prone disorder, xeroderma pigmentosum, owing to the enzyme’s ability to accurately bypass UVR-induced thymine dimers." (PMID 34900730, 2021). "In humans, mutations of POLH are found in one form of xeroderma pigmentosum, the XP variant complementation group or XP-V." (PMID 34589668, 2020). "Xeroderma pigmentosum (XP) is a hereditary disease caused by mutations of eight different genes of the NER pathway, or POLH, here together named the nine XP genes." (PMID 35174087, 2022). "Notably, the fly PolH mutants may provide in vivo models of a variant form of xeroderma pigmentosum, a disease characterized by increased incidence of UV-induced skin cancers caused by mutations in human PolH." (PMID 31933406, 2020). "Xeroderma pigmentosum (XP) is a rare autosomal recessive disease caused by pathogenic variants in seven nucleotide excision repair genes (XPA to XPG) and POLH involved in translesion synthesis." (PMID 39621777, 2024). "Inherited defects in the gene encoding POLH (XPV) are associated with the rare, sun-sensitive, cancer-prone disorder, xeroderma pigmentosum, due to the loss of the ability of POLH to accurately bypass UVR-induced thymine dimers." (PMID 38068959, 2023). "Biallelic pathogenic variants in one of the seven NER genes coding for the so-called complementation groups, XPA, ERCC3, XPC, ERCC2, DDB2, ERCC4, ERCC5, the NER gene ERCC1, and the gene coding for XP variant, POLH, are the causes of the rare hereditary disease Xeroderma pigmentosum (XP)." (PMID 35174087, 2022). "A key TLS Pol in humans, Pol eta (encoded by the POLH gene), was initially identified as the gene mutated in a variant form of Xeroderma Pigmentosum (XP), a genetic disorder characterized by extensive sensitivity to ultraviolet (UV) rays and predisposition to sunlight-induced skin cancer." (PMID 34815340, 2021). "Patients of a variant form of Xeroderma Pigmentosum (XPV), which have deficiencies in the POLH gene, show high photocarcinogenic sensitivity in skin regions exposed to sunlight, and cells removed from such patients are also sensitive to UV-induced mutations." (PMID 33015036, 2020). "These diseases include xeroderma pigmentosum (XP) which is due to a defect in one of approximately eleven XP associated genes (including XPA, ERCC3 (XPB), XPC, and POLH (XPV))." (PMID 23285288, 2012). "TTD is a distinct condition from Xeroderma Pigmentosum (XP) caused by mutation in eight XP‐associated genes: XPA, XPD (ERCC2), XPB (ERCC3), XPF (ERCC4), XPG (ERCC5), XPC, XPE (DDB2), and a variant form related to the POLH gene." (PMID 39976384, 2025). "To further challenge the assay, we used fibroblasts from patients with xeroderma pigmentosum variant (XP‐V) lacking functional DNA polymerase eta (Polη, encoded by the gene POLH), a key enzyme involved in translesion synthesis (TLS) and DDT, as well as POLH‐complemented counterparts." (PMID 41376455, 2025).
skin cancer (15 papers, 2010 to 2025). "Xeroderma pigmentosum variant (XP-V) cells, deficient in DNA polymerase eta (pol eta), exhibit a heightened risk of skin cancer due to impaired TLS." (PMID 40794023, 2025). "Patients with the skin cancer-prone genetic condition xeroderma pigmentosum variant lack functional Pol η due to mutations in POLH (originally called hRAD30)." (PMID 39457395, 2024). "Inactivating mutations in the human POLH gene encoding the Y-family DNA polymerase Pol η causes the skin cancer-prone genetic disease xeroderma pigmentosum variant (XPV)." (PMID 39457395, 2024). "XPV is a rare inherited human disorder characterized by increased incidence of sunlight-induced skin cancers that is caused by inactivating mutations of POLH." (PMID 22973298, 2012). "Finally, the article reviews recent findings indicating that human DNA polymerase eta normally suppresses these non‐canonical UV mutation classes, which can potentially explain why canonical C>T substitutions predominate in human skin cancers." (PMID 38884048, 2024). "Comparison of the mutation spectra of XPV−/− tumors and UV‐irradiated rad30∆ yeast reveals much greater similarity than the mutation spectra of sporadic skin cancer and UV‐irradiated WT yeast, in which DNA polymerase eta is active." (PMID 38884048, 2024). "POLH deficiency causes one form of the skin cancer-prone disease xeroderma pigmentosum variant (XPV) and cisplatin sensitivity, but the functional impacts of its germline variants remain unclear." (PMID 36982269, 2023). "Although not conclusive yet, a genetically hypoactive status of pol η might potentially increase a cancer risk in humans, in that heterozygous POLH-deficient mice show an increased incidence of UV-induced skin cancer." (PMID 36982269, 2023). "POLH deletion results in a genetic predisposition to skin cancer." (PMID 33374731, 2020). "Thus, other types of skin cancer are also good candidates for the identification of POLH cancer-predisposing alleles." (PMID 22973298, 2012). "DNA polymeraseη is coded by POLH gene which is one of the 150 human DNA repair genes, whose defection results in Xeroderma Pigmentosum Variant (XP-V) syndrome, manifesting highly sensitivity to UV radiation and a trend to develop skin cancer." (PMID 21110884, 2010). "Search terms were “Xeroderma pigmentosum”, “XP”, “XPC”, “Nucleotide excision repair”, “NER”, “POLH”, “Dry pigmented skin”, and “UV sensitive syndrome” meshed with the terms “Skin cancer”, “Melanoma”, and “NMSC”." (PMID 35898688, 2022). "Five mL of blood were collected from suspected XP-V patients (individuals with sun sensitivity and who develop skin tumors on exposed sites) and the genomic DNA purified from isolated memory B cells was used for both POLH sequencing and the immunoglobulin JH4 intron amplification and sequencing." (PMID 31992747, 2020). "A global analysis of the status of Pol eta in skin cancer cells demonstrated that, in a cohort of patients showing no changes in the sequence of the Pol eta coding gene, the POLH mRNA expression was either decreased or increased in skin tumor tissue compared with normal tissue." (PMID 32076806, 2020).
Xeroderma pigmentosum variant (11 papers, 2012 to 2025). Xeroderma pigmentosum variant is a milder subtype of xeroderma pigmentosum (XP; see this term), a rare genetic photodermatosis characterized by severe sun sensitivity and an increased risk of skin cancer. "We report a case of a patient with xeroderma pigmentosum variant type who developed early‐onset dementia, in which two novel gene variants in POLH and TREM2 were found." (PMID 32935933, 2020). "Inherited loss-of-function POLH mutations cause Xeroderma Pigmentosum Variant (XPV), a disease characterized by skin UV hypersensitivity and predisposition to skin cancer." (PMID 30347795, 2018). "In the case of xeroderma pigmentosum variant (XP-V), patients express a truncated POLH, which reduces the expression and activity of DNA polymerase η (Pol η)." (PMID 35935942, 2022). "Xeroderma pigmentosum variant type (XPV) is associated with pathogenic variants in POLH on chromosome 6, and no neurological dysfunction has been seen in these cases." (PMID 32935933, 2020).
melanoma (9 papers, 2012 to 2025). A malignant, usually aggressive tumor composed of atypical, neoplastic melanocytes. "Conversely, downregulation of POLH and PRIMPOL, which are essential for DNA damage tolerance, particularly against UV-induced lesions, predisposes to melanoma." (PMID 41465101, 2025). "DNA polymerase levels can be altered in human tumors; specifically, POLH is upregulated or amplified in melanoma, esophageal and ovarian cancer, which contrasts with the HRasG12V-induced depletion we measured above in nontumorigenic cells." (PMID 33961649, 2021). "Performing germline/tumour whole-exome sequencing of 44 stage III/IV melanoma patients we identified pathogenic germline mutations in CDKN2A, CDK4, ATM, POLH, MRE11A, RECQL4 and XPC, affecting 7/44 patients." (PMID 33077847, 2020). "However, three missense POLH mutations were identified in three out of 201 melanoma patients, and these mutations were absent in 176 healthy controls." (PMID 22973298, 2012).
lung cancer (4 papers, 2018 to 2022). A malignant neoplasm involving the lung. "Previously, it has been found that loss of POLH significantly attenuates resistance to CDDP in both CDDP-sensitive and -resistant lung cancer cell lines." (PMID 36293346, 2022).
breast carcinoma (3 papers, 2021 to 2025). "For example, in the human breast carcinoma cell line ZR-75-1, A-to-I editing of ATM and POLH transcripts is enhanced, accompanied by elevated expression levels of these genes, as shown by RNA-seq analysis." (PMID 41164819, 2025).
Fanconi Anaemia (2 papers, 2020 to 2022). "Relevant to the adaptation of TRD to arid conditions, ten selected genes (including SLX4, FANCF, FANCG, FANCI, ATR, and POLH) were related to the fanconi anemia pathway (bta03460, p < 0.01) involved in DNA repair, DNA replication fork stability, and other cellular processes." (PMID 33072165, 2020). "In addition, the top two enriched KEGG pathways were: 1) the Fanconi Anaemia pathway (represented by ATR, BRIP1, ERCC4, FANCC and POLH) and the FoxO signalling pathway (represented by CREBBP, NLK, PRKAA2, PRKAB1, PTEN and STK11)." (PMID 35768547, 2022).
head and neck squamous cell carcinoma (2 papers, 2022 to 2024). A squamous cell carcinoma that arises from any of the following anatomic sites: lip and oral cavity, nasal cavity, paranasal sinuses, pharynx, larynx, and salivary glands. "During their retrospective analysis of squamous cell carcinomas of head and neck (HNSCC), Zhou and colleagues reported that low POLH expression was significantly associated with high complete response rate (p = 0.03) in patients treated with platinum- and gemcitabine-based chemotherapy." (PMID 36428691, 2022). "Further, POLH mRNA is over-expressed in a subset of cancers, including non-small cell lung cancer and head and neck squamous cell carcinoma, as a result of amplification of the POLH genomic locus on chromosome 6." (PMID 39457395, 2024).
ovarian carcinoma (2 papers, 2021 to 2024). A malignant neoplasm originating from the surface ovarian epithelium. "POLH mRNA expression is also regulated by the miRNAs miR-93 and miR619, which modulate the sensitivity of ovarian cancer stem cells to platinum-based chemotherapeutic agents." (PMID 39457395, 2024). "It has recently been reported that the long non-coding RNA taurine upregulated gene 1 (TUG1) up-regulates Pol η levels in ovarian cancer cell lines by binding to miR487-3p and miR-6088, preventing these miRNAs from targeting POLH mRNA." (PMID 39457395, 2024).
triple-negative breast carcinoma (2 papers, 2023). An invasive breast carcinoma which is negative for expression of estrogen receptor (ER), progesterone receptor (PR), and human epidermal growth factor receptor 2 (HER2). "Furthermore, rare missense variants within PALB2 domains WD1, domain for stimulation of POLH DNA synthesis and domain for interaction with RAD51, BRCA2 and POLH were significantly associated with increased risk of triple-negative breast cancer." (PMID 37790698, 2023).
bladder cancers (1 paper, 2023). "POLH overexpression has been linked to the development of chemoresistance in several cancers, including lung, ovarian, and bladder cancers." (PMID 38068959, 2023). "Consistent with the known biochemistry, elevated POLH expression is correlated with reduced cisplatin sensitivity in models of lung and bladder cancer." (PMID 38068959, 2023).
cervical cancer (1 paper, 2022). A primary or metastatic malignant neoplasm involving the cervix. "To determine if the same was true for TLS genes other than the TLS polymerases (POLH, POLI, POLK, REV1, and REV3L), we segregated the cervical cancers in the TCGA database based on whether they did or did not have increased expression of at least one TLS gene." (PMID 36266721, 2022).
dementia (1 paper, 2020). Loss of intellectual abilities interfering with an individual's social and occupational functions. "We report two novel variants on chromosome 6 genes POLH and TREM2 in the same patient, associated with a phenotype of XPV and early‐onset dementia." (PMID 32935933, 2020).
frontotemporal dementia (1 paper, 2020). Frontotemporal dementia (FTD) comprises a group of neurodegenerative disorders, characterized by progressive changes in behavior, executive dysfunction and language impairment, as a result of degeneration of the medial prefrontal and frontoinsular cortices. "Whole‐exome sequencing identified novel homozygous variants in POLH c.638C>G (p.Ser213*) and TREM2 c.154C>T (p.Arg52Cys), classifying the patient as XPV and suggesting that her frontotemporal dementia phenotype could be related to the variant in TREM2." (PMID 32935933, 2020).
gastric cancer (1 paper, 2021). A primary or metastatic malignant neoplasm involving the stomach. "Twenty-four hyper-mutated tumors were identified only in colorectal and gastric cancers, with a significant enrichment of mutations in the polymerase genes (POLE, POLD1, and POLH) and mismatch repair (MMR) genes." (PMID 34594355, 2021).
hereditary cancer syndromes (1 paper, 2017).
invasive breast carcinoma (1 paper, 2016). A carcinoma that infiltrates the breast parenchyma. "This also accounted for TpC>G and TpC>A mutations, indicating that POLH contributes to the increased TpC>G and TpC>A transversions in APOBEC3B expressing invasive breast cancers." (PMID 26926109, 2016). "In contrast to all other family members, POLH expression showed a positive pro-mutagenic correlation with both C and TpC transversions, suggesting an involvement of POLH in bypassing APOBEC3B-induced AP-sites in invasive breast cancer." (PMID 26926109, 2016).
leukemia (1 paper, 2025). A malignant (clonal) hematologic disorder, involving hematopoietic stem cells and characterized by the presence of primitive or atypical myeloid or lymphoid cells in the bone marrow and the blood. "XP-V patients with POLH mutations are not known to develop BM failure or leukemia." (PMID 41165757, 2025).
viral infection (1 paper, 2025). "To test that, we assessed whether HSCs are sensitive to PolH depletion in vivo using the viral infection/BMT model using 2 different shRNAs to PolH." (PMID 41165757, 2025).